BRCA1 (BRCA1 DNA repair associated)
Diseases named in the same sentence as BRCA1 in open-access papers (continued):
Sharing a sentence is not in itself a finding about the gene and the disease.
breast tumors (continued). "Analysis of the recurrent regions of chromosomal instability in BRCA1 or BRCA2 mutated breast tumors may point to loci and/or genes involved in development and progression of BRCA-associated hereditary breast cancer." (PMID 20735817, 2010). "The vast majority of BRCA1 mutation-related breast tumors represent basal-like subtype." (PMID 20426817, 2010). "Similarly, to determine which CNAs occur significantly more often in the human BRCA1-mutated breast tumors compared to the control tumor group, we used comparative-KC-SMART on aCGH data from human tumors." (PMID 20735817, 2010). "In recent years it is becoming clear that phenotypic features of TNBC/BLBC may also apply to the majority of hereditary BRCA1-mutated breast tumors." (PMID 21118481, 2010). "However, methylation of the BRCA1 gene promoter and loss of BRCA1 gene expression are significantly associated and occur frequently in sporadic breast tumours." (PMID 19589159, 2009). "Another possible explanation for the selective overexpression of EZH2 in BRCA1-deficient breast tumors could involve a role of EZH2 in the cell of origin." (PMID 19709408, 2009). "The availability of a small molecule inhibitor such as DZNep allowed us to test whether pharmacological targeting of EZH2 function provides a selective approach to kill BRCA1-deficient breast tumor cells." (PMID 19709408, 2009). "Moreover, breast tumors in BRCA1-mutation carriers show invariably loss of the other BRCA1 allele, indicating that selection for loss of BRCA1 expression is not achieved by high levels of EZH2." (PMID 19709408, 2009). "However, although BRCA1 mutations in sporadic cancer are rare, there are indications that a significant proportion of sporadic breast tumors share traits with BRCA1-deficient tumors, a feature termed BRCAness." (PMID 19709408, 2009). "A similar analysis of breast tumors arising in carriers of BRCA1 mutation, analyzed from a different dataset (The Netherlands Cancer Institute), revealed highest resemblance in 17 of 18 cases to basal-A lines (not shown), while two BRCA2 mutation associated cases most resembled luminal cell lines." (PMID 19582160, 2009). "Finally, we show that breast tumor cells with a mutation in BRCA1 have increased sensitivity towards QAP 1 as compared to cells reconstituted with BRCA1." (PMID 19128485, 2009). "Moreover, Lakhani and colleagues tested five basal markers (CK-14, CK-5/6, CK-17, epidermal growth factor and osteonectin), all of which were significantly associated with BRCA1 tumours as compared with unselected breast tumours." (PMID 18275599, 2008). "However the late age at which these breast tumors developed argues against their being caused by mutations in the BRCA1 or BRCA2 genes." (PMID 18307792, 2008). "However, somatic mutations of BRCA1/2 in sporadic breast tumours, as well as in other cancer types, are very rare." (PMID 17242703, 2007). "This raises the possibility that breast tumours derived from patients with BRCA1 mutation might have a higher rate of WWOX alterations." (PMID 15266310, 2004). "Furthermore this pilot analysis revealed a gene cluster that differentially expressed genes related to cell substrate formation, adhesion, migration and cell organization in BRCA1-mutated tumours compared to sporadic breast tumours." (PMID 11506493, 2001). "The co-occurrence of BRCA1 loss and TAZ gain may represent a genetic feature of basal-like breast tumors and may provide a rationale for the aggressiveness of BRCA1 mutated tumors, where inactivation of the BRCA1 tumor suppressor may also have the effect of activating the TAZ oncogenic program." (PMID 37887275, 2023). "Therefore, we hypothesized that a loss of NORE1A could explain how Her2+/BRCA1− breast tumors overcome the OIS/HIS senescence responses." (PMID 37627161, 2023).
breast tumors (continued). "This may be particularly important for breast tumors that are both Her2+ and deficient for BRCA1." (PMID 37627161, 2023). "In this cohort study of a large, consecutive series of 8396 Chinese patients with primary invasive breast cancer in a single center, we investigated whether BRCA1/2 variant carriers could safely undergo BCT when the breast tumor was suitable for this procedure." (PMID 33890992, 2021). "The observation that the PDS gene Signature-3 score is higher in TCGA breast tumors with somatic damaging mutations of BRCA1 gene might suggest that deficiency in homologous recombination pathway may lead to high micronuclei accumulation as observed previously in osteosarcoma U2OS cancer cells." (PMID 34139015, 2021). "However, because BRCAX breast tumors were also included in the HBC group, we believe it is a limitation of the present study, and further studies are needed to investigate target genes and signaling pathways specifically deregulated in BRCA1/2-mutated breast tumors." (PMID 32087690, 2020). "Therefore, our findings suggest that these miRNAs could be suitable in discriminating hereditary BRCAX breast tumors from BRCA1/2-mutated breast tumors." (PMID 32087690, 2020). "In addition, alternative splicing expression profile was also successfully used in several studies aiming to discriminate subtypes of breast tumors, and specific gene expression profiles have also been identified for BRCA1, BRCA2 and CHEK2-associated breast tumors." (PMID 29108258, 2017). "Therefore, other somatic events that inactivate BRCA1 can predispose to sporadic breast tumours." (PMID 29259228, 2017). "Also, BRCA1 mutated breast tumors are frequently reported to be of the basal-like intrinsic subtype, opposed to breast tumors from CHEK2 mutation carriers, which are reported to be mostly steroid hormone receptor positive (progesterone receptor/progesterone receptor (ER/PR) positive)." (PMID 26553136, 2015). "Furthermore, there were significant associations between BRCA1 promoter methylation and clinicopathological characteristics in breast tumors, such as lymph node metastasis, high histological grade, ER-negative, PR-negative, triple-negative phenotype and reduced or lack expression of BRCA1 protein." (PMID 26643130, 2015). "Integration of breast imaging data with family history and breast tumor markers could be formally assessed by estimating the added value of our image-based probability score to existing statistical models that are used to predict BRCA1/2 mutations." (PMID 25159706, 2014). "Indeed, when extending these analyses to other hypermutators, that is, UV-light-induced melanoma, tobacco smoke-induced small cell lung adenocarcinoma (SCLC), as well as breast tumors deficient for BRCA1 or EM tumors proficient for MMR, patterns were clearly dissimilar from the matched germ-line." (PMID 25085081, 2014). "However, somatic BRCA1 mutations are rarely found in sporadic breast tumours." (PMID 22016618, 2011). "Indeed, breast tumors from BRCA1-mutation carriers are sensitive to inhibition of DNA single-strand break (SSB) repair by poly(ADP-ribose) polymerase (PARP) inhibitors and to chemotherapy that causes DSBs, such as platinum drugs, alkylating agents and topoisomerase I poisons." (PMID 21118481, 2010). "Importantly, up-regulation of Rad51 was a common feature of BRCA1-deficient breast tumors." (PMID 20205718, 2010). "In summary, we have studied the functions of BRCA1 and its downstream signaling in breast tumor formation in mice." (PMID 40157910, 2025).
breast tumors (continued). "Accumulating evidences indicated that myeloid cells are the most abundant leukocytes in breast tumours, and we herein decoded the cellular complexity of myeloid cells in the patients with BRCA1-WT and BRCA1-MT." (PMID 40904511, 2025). "The BRCA1 expression was also modified as a result of the breast tumor cells being in contact with the GF-based scaffolds compared with the normal cells." (PMID 39940603, 2025). "Using a semi‐supervised method, we developed HRD classifiers from 1404 breast tumours across two datasets based on their BRCA1/2 status, demonstrating improved HRD identification when aggregating different data types." (PMID 40260608, 2025). "Conversely, in the gender-unselected population, less than 2% of HER2-low breast tumors seemed to carry PVs in BRCA1/2 genes, and PVs in these genes were significantly more frequently identified in HER2-low patients." (PMID 38339299, 2024). "Similar to BRCA1 or BRCA2 deletion, copy number loss of each gene in the CK2–HTATSF1–TOPBP1 axis predicted higher HRD scores in TCGA breast tumors." (PMID 38762174, 2024). "It should be noted that according to our previous studies, the frequency of aberrations in the number of copies of the BRCA1 gene in breast tumors is 53.3% (48/90 cases), of which the frequency of deletions and amplifications is 35.6% and 17.7%, respectively." (PMID 37628606, 2023). "We induced breast tumors in Balb/c mice and tested the formulations (NP, BRCA1 + NP and BRCA2 + NP) in vivo." (PMID 36631481, 2023). "Another study in Brca1-mutant mice showed somewhat different results, namely that breast tumor incidence of oophorectomized and intact mice remains similar until 135 days post-oophorectomy." (PMID 37046756, 2023). "When we examined the effects of re-expressing NORE1A in NORE1A-negative MCF-7 breast tumor cells, we found that its ability to induce senescence was impaired if we knocked down BRCA1." (PMID 37627161, 2023). "Germline mutations or deletions in BRCA1 and BRCA2 genes are associated with breast tumor formation." (PMID 37438760, 2023). "In this regard, the work was aimed to evaluate CNA and mutations of the BRCA1, BRCA2, and PALB2 genes in the breast tumor of patients and their predictive and prognostic potential." (PMID 37628606, 2023). "The GEO dataset GSE4582741 containing primary breast tumors with different molecular types allowed us to compare the BRCA1 expression levels in different types of ER+ tumors." (PMID 34996912, 2022). "In line with our mouse tumor results, patient BRCA1-mutant breast tumors have significantly higher enrichment scores of M2 macrophage gene signature than BRCA1-mutant ovarian tumors." (PMID 35641483, 2022). "Based on the results of the prospective study, it can be stated that a preliminary assessment of BRCA1 expression and the presence of a deletion in the biopsy material of a breast tumor was a good predictive and prognostic marker for prescribing treatment." (PMID 36613648, 2022). "We first demonstrate that G418 treatment restores BRCA1 FL protein synthesis in HCC1395, a human breast tumor cell line carrying the R1751X mutation." (PMID 35837282, 2022). "It should be noted that the frequency of BRCA1 gene copy number aberrations in breast tumors was 53.3% (48/90 cases)." (PMID 36613648, 2022).
breast tumors (continued). "Using AeQTL, we discovered that aggregated rare germline truncations in cis exomic regions are significantly associated with the expression of BRCA1 and SLC25A39 in breast tumors." (PMID 33691015, 2021). "Soon after the publication of the synthetic lethality of PARP inhibitors and HR deficiency, Rottenberg and colleagues explored the use of PARP inhibitors for cancer treatment in vivo using a Brca1 mouse model of breast tumors." (PMID 33923105, 2021). "Our novel results describe a state of increased gene expression variability in BRCA1-related and basal-like breast tumours." (PMID 34287743, 2021). "The aim of our study was to evaluate the effect of BRCA1-deleted (BRCA1+/−) iMSCs on breast tumor development and progression, compared to iMSCs that contained two copies of BRCA1 (BRCA1+/+ iMSCs)." (PMID 33513753, 2021). "From a pathological perspective, BRCA1 and BRCA2-associated breast tumors have been shown to differ on both morphological and molecular levels." (PMID 33117676, 2020). "Breast tumors were mostly invasive ductal carcinomas (occurring in milk ducts) for both BRCA1 (80%) and BRCA2 (83%) carriers." (PMID 32481735, 2020). "Larsen and colleagues studied 183 breast tumours (33 BRCA1, 22 BRCA2) and developed a 110-probe signature to classify BRCA1 breast tumour within the basal-like subtype with an accuracy of 83% (sensitivity: 82%, specificity 85%)." (PMID 33081408, 2020). "Poly (ADP-ribose) polymerase (PARP) inhibitors (PARPi) can be used as a targeted treatment for germline BRCA1/2-positive BC patients with HER2-negative metastatic breast tumors." (PMID 33120919, 2020). "A recent meta-analysis of RNA-seq data from multiple studies revealed that the BRCA1 and DNA damage response pathway was upregulated in breast tumors compared to healthy breast tissues, in addition to the estrogen-mediated S-phase entry pathway." (PMID 32678032, 2020). "The main goal of this study was to identify the principal characteristics that differentiate a family with BRCA1/BRCA2 pathogenic mutations from those with a VUS alteration and even from those BRCA1/BRCA2 WT and with sporadic breast tumors." (PMID 31244284, 2019). "Promoter hypermethylation of BRCA1 has been reported in 13% of sporadic breast tumors, with promoter hypermethylation of FANCC (PALB2), FANCO (RAD51C), and FANCF also reported." (PMID 31320901, 2019). "Breast tumors with BRCA1 methylation also show higher histological grade, like that of BRCA1-mutated tumors." (PMID 30934991, 2019). "Invasive ductal carcinoma is the most common histological breast tumor typeobserved in BRCA1 and BRCA2 carriers.Other histological subtypes, including medullary and tubular carcinoma, are alsofound in this subgroup of patients (Mavaddatet al., 2012)." (PMID 31067289, 2019). "In primary human breast tumors, there is a positive correlation between protein levels of BRCA1 and DNMT1." (PMID 30558184, 2018). "We identified 140 differentially expressed miRNAs, 9 of which were also differentially expressed in human BRCA1 breast tumours or familial non-BRCA1 patients and during normal gland development." (PMID 30323900, 2018). "According to a recently published study, only 9% of BRCA1-related breast tumours and 13% of BRCA2-related breast tumours were HER2 positive." (PMID 29928469, 2018). "The results revealed that there is a high frequency of BRCA1 underexpression in both triple-negative and luminal breast tumors." (PMID 28646826, 2018). "As expected, a high expression of β-hCG was observed in breast tumor tissues of BRCA1 conditional knockout WAP-Cre; BRCA1KO/CO mice." (PMID 28869585, 2017). "Other than germline mutation status, we also investigated the methylation profile of BRCA1 in breast tumor and normal counterpart." (PMID 27926510, 2017).
breast tumors (continued). "Retention of the normal BRCA1 or BRCA2 allele (absence of locus-specific loss of heterozygosity (LOH)) is observed in 7% of BRCA1 ovarian, 16% of BRCA2 ovarian, 10% of BRCA1 breast, and 46% of BRCA2 breast tumors." (PMID 28831036, 2017). "One BRCA1 and one BRCA2 breast tumor each had somatic pathogenic mutations in the corresponding gene, at 21 and 35% allele frequency, respectively." (PMID 28831036, 2017). "The BRCAness profile is generated by comparing gene expression between BRCA1/2 mutant familial tumors with sporadic breast tumors." (PMID 29146938, 2017). "The presence of methylation in the promoter region of BRCA1 in sporadic breast tumors has been reported in several studies." (PMID 27926510, 2017). "The authors also found that NEAT1 increased the malignant biological behaviors of BRCA1- knockdown breast neoplasm cells through suppressing mir-129-5p and subsequently enhancing the expression of oncogene WNT4." (PMID 28118609, 2017). "In the sequence, to classify the samples as methylated or unmethylated, a cut-off of 4% was set, and, using this stratification, BRCA1 promoter hypermethylation was found in 2 of 88 (2.3%) breast tumor samples analyzed." (PMID 27926510, 2017). "In this study, we developed a new computational method to infer the level of cell proliferation in breast tumor samples by referring to gene expression profiles generated by RNAi-mediated knockdown of BRCA1 or RAD51 in MCF-10A cells." (PMID 27788678, 2016). "Of note, complete inversions were also significantly enriched amongst BRCA1 and BRCA2 germline-deficient breast tumours (P=2 × 10−16)." (PMID 27615322, 2016). "The purpose of this multicenter study was to evaluate Multiplicom's BRCA MASTR Dx kit to detect clinically important variants in BRCA1 and BRCA2 in FFT derived ovarian and breast tumor samples." (PMID 27793035, 2016). "BRCA1 promoter hypermethylation in blood and breast tumor-derived DNA has been reported in the literature." (PMID 27902704, 2016). "With proteomic analysis of breast tumor GEMM-derived secretomes, we identified a series of released proteins associated with BRCA1 status." (PMID 27566577, 2016). "For example, BRCA1 hypermethylation was observed in 13/143 (9.1%) sporadic breast tumours, most of which (9/13) also show diminished BRCA1 expression." (PMID 27666291, 2016). "The silencing of BRCA1 via promoter methylation has also been observed in breast tumors, including those arising in women with increased constitutional DNA methylation at this region." (PMID 27902704, 2016). "Familial BRCA1 or BRCA2 mutant breast tumors tend to have a TNBC phenotype and often exhibit extreme levels of genomic instability." (PMID 27959926, 2016). "Genomic features have been selected to infer BRCAness by comparing BRCA1/2 mutant samples with hereditary breast tumor samples." (PMID 27788678, 2016). "This suggests a possibility that a small proportion of the epithelial cells with BRCA1 promoter methylation can be precursor cells from which BRCA1-methylated breast tumors originate." (PMID 27413552, 2016). "DNA methylation of the BRCA1 promoter is a moderately frequent event in sporadic breast tumours and an alternative mechanism of BRCA1 inactivation." (PMID 27463681, 2016). "Recently, a functional link between BRCA1 and miRNAs has been described but few reports are available about miRNA profiling in familial breast tumors also with respect to BRCA status." (PMID 25333258, 2015). "Altogether, these indicate that the patients with BRCA1-methylated breast tumors are likely to have little benefit from traditional hormone or targeted therapies." (PMID 26643130, 2015). "We have also applied PCA-based DDL to the subset of basal-like breast tumors (bottom left) which showed the specific role of BRCA1 gene in this subtype confirming a known fact." (PMID 26271256, 2015).